REG3G (regenerating family member 3 gamma)
Diseases named in the same sentence as REG3G in open-access papers (continued):
Sharing a sentence is not in itself a finding about the gene and the disease.
infection (continued). "During infection, IL-22 confers protection to the host by stimulating epithelial cells to produce antimicrobial proteins, including the C-type lectins Reg3β and Reg3γ, which exhibit direct antimicrobial activity against a subset of bacterial pathogens (7, 9, –, 13)." (PMID 38557196, 2024). "Reg3γ is an important factor in innate immunity and plays an important role in maintaining the dynamic balance among mammalian gut microbes and protecting the body from pathogen infection." (PMID 35095784, 2021). "In addition, we addressed the effect of exogenous IL-33 application on REG3γ expression in vivo during acute CR infection." (PMID 33654214, 2021). "Similarly, the antimicrobial factor Reg3γ was increased during infection, as was the multifunctional cytokine IL-22." (PMID 31848276, 2019). "Thus, an up-regulated production of the REG3G transcripts seems reasonable in the early stage of infection." (PMID 30161141, 2018). "The infection up-regulated the expression of resistin-like molecule beta (Retnlb), angiogenin 4 (Ang4), and mucin 2 (Muc2) but down-regulated regenerating islet-derived protein 3 gamma (Reg3γ) and lysozymes 1 (Lyz1) and 2 (Lyz2)." (PMID 26377648, 2015). "Reg3γ, a protein with antibacterial and regenerative functions released by epithelial cells in response to infection and damage, and the alarmin HMGB1 were also detected in higher amounts in the BALF of C57BL/6J than Elane−/− mice, consistent with the increased tissue damage." (PMID 25166912, 2014). "Employing qRT-PCR, we observed that Reg3γ expression was significantly induced in IECs by the day of colonic colonization (4 DPI) and continued to increase to the peak of infection." (PMID 30940698, 2019). "Infection-induced alterations in ileal AMP expression seen in N. brasiliensis-infected WT mice, including up-regulation of Retnlb and Ang4 and down-regulation of Reg3γ, disappeared almost entirely in IL-13−/− or STAT6−/− mice." (PMID 26377648, 2015). "In mice that were both treated and challenged (D1(7d) group), the expression of Reg3β, Reg3γ and Lncn2 was even more pronounced compared to mice that were only challenged (CTL, p < 0.05), suggesting that protection against infection may be related to the expression of these molecules." (PMID 41156807, 2025). "Additional analysis of several cytokines (Tnf-α, Il-6, IL-1β, and IFN-γ) and antimicrobial factors (Reg3γ, S100a8, and S100a9) found to increase during RIMD infection showed a similar trend, i.e., they were also strongly induced by infection with POR1 or POR2 but not POR3." (PMID 31848276, 2019). "Infection of paraoxon-pretreated mice also led to a significant enhancement in the expression of Defa1 (2.3-fold), MMP-7 (1.6-fold), and Ang-4 (4.3-fold) antimicrobial proteins, but not Reg3γ which was already upregulated by paraoxon treatment." (PMID 29616040, 2018).
tumor (8 papers, 2017 to 2025). "In addition, other genes activated by PPARδ, such as CSF1 (colony stimulating factor 1) and REG3G (regenerating islet-derived protein 3 gamma), encode secreted proteins that recruit myeloid-derived suppressor cells to the tumor microenvironment." (PMID 40247913, 2025). "In PDAC, activation of JAK2/STAT3 cell signaling with the participation of REG3G was found to induce immunosuppression by limiting the antigenicity of tumor cells, suppressing CD8+ cell function, causing variable expression of Th2 cytokines and increasing the proliferation of tumor cells." (PMID 32488850, 2020). "Numerous changes based on HGFL-RON signaling are downregulated (e.g., lipocalin-2 [LCN2]) and a few upregulated (regenerating family member 3 gammas [Reg3G]) in tumor cells." (PMID 35626096, 2022). "The results showed that, compared with the control groups, the lnc-REG3G-3-1 in the knockdown group was significantly decreased in tumor tissues, whereas the miR-215-3p level was remarkably increased." (PMID 32903414, 2020). "Conditioned media from Reg3g-treated DCs of TBM inhibited apoptosis and promoted Panc02 cell growth, consistent with in vivo results showing tumor enhancement induced by Reg3g overexpression." (PMID 28880262, 2017). "To further investigate the role of CD8+ T cells in Reg3g-mediated tumor progression, we treated TBM with anti-CD8 mAb or shReg3g lentiviral particles." (PMID 28880262, 2017). "The data indicated that downregulation of Reg3g inhibited tumor growth, and that CD8+ T-cell deletion abolished the effect." (PMID 28880262, 2017). "To further investigate how Reg3g regulated tumor inflammatory responses through DCs, we isolated DCs from control, TBM, and Reg3g-overexpressed TBM." (PMID 28880262, 2017). "The results showed that Reg3g downregulation inhibited tumor growth, whereas Reg3g overexpression increased tumor growth." (PMID 28880262, 2017). "This is in agreement with our previous study showing that REG3A accelerated tumor growth via STAT3 signaling, and with our present findings indicating that Reg3g promoted tumor growth by suppressing immune responses." (PMID 28880262, 2017). "Consistent with its effects on cytokine secretion, Reg3g overexpression also reduced tumor expressions of mRNAs for Th1 cytokines IFN-γ and IL-12, and increased mRNAs for Th2 cytokines such as TGF-β and IL-10." (PMID 28880262, 2017). "In this study, Reg3g-regulated tumor immunity was evaluated in tumor-implanted murine models, immune cells, and tumor microenvironment." (PMID 28880262, 2017). "In addition, we also found that Reg3g elevated interactions between inhibitor ligand PD-L1 in DCs and PD-1 in T cells, resulting in the suppression of tumor-specific T-cell activation." (PMID 28880262, 2017). "In summary, our findings reveal an important and novel tumor-promoting role of Reg3g in PDAC." (PMID 28880262, 2017). "It is a matter of debate as to whether Reg3g promotes the proliferation, cytokine secretion, migration, and invasion of Panc02 cells directly, or indirectly by influencing interactions between DCs and tumor cells." (PMID 28880262, 2017). "We postulate that the overexpression of Reg3g increases EGFR, but suppresses tumor antigenicity by upregulating the levels of Ki67 and inhibiting the expression of caspase-3 and MHC-I in tumors." (PMID 28880262, 2017). "To further characterize the role of Reg3g in tumor growth, we treated tumor-bearing mice (TBM) with shReg3g or pReg3g lentiviral particles to induce Reg3g downregulation or overexpression, confirmed by western blot." (PMID 28880262, 2017). "Reg3g produces these effects by activating the JAK2/STAT3 signaling pathway in DCs, triggering the generation of an immunosuppressive tumor microenvironment." (PMID 28880262, 2017). "In vitro, Reg3g upregulated EGFR in DCs, activated heme oxygenase-1 (Hmox1) involved JAK2/STAT3 signaling, raised levels of Th2 cytokines in and suppressed maturation of DCs, and enhanced tumor cell proliferation." (PMID 28880262, 2017).
tumor (continued). "By interacting with PD-1/PD-L1, Reg3g also promoted differentiation of Tregs and recruitment of MDSC, retarded maturation of DCs and inactivation of CD8+ T cells, and suppressed cross-priming of CD8+ T-cell responses by DCs in tumor-bearing mice." (PMID 28880262, 2017). "Knockdown of Reg3g delayed tumor development in normal mice, but not in CD8+ T-cell-deficient mice." (PMID 28880262, 2017). "Thus, Reg3g seems to suppress cytotoxic activities of CD8+T cells by regulating the maturation and function of DCs, thereby blunting immune responses and promoting tumor growth." (PMID 28880262, 2017). "Suppression of Reg3g failed to inhibit tumor growth in the absence of CD8+ T cells." (PMID 28880262, 2017).
cancer (5 papers, 2013 to 2025). A tumor composed of atypical neoplastic, often pleomorphic cells that invade other tissues. "The network surrounding Il10ra shows that many of them are cancer related, e.g., Reg3g, Aoc1, Mep1a, Irf7, Gas6, B3gnt7, Tap1, Tgm2, and Nos2." (PMID 33396408, 2020). "Additionally, decreased levels of the antimicrobial protein regenerating islet‐derived protein 3 gamma (REG3γ) facilitate microbial translocation across the barrier, resulting in chronic inflammation and subsequent cancer progression." (PMID 40236776, 2025). "REG3G, ACAT2, and ATF5 have also been found in various cancers." (PMID 31148949, 2019).
bacterial infection (4 papers, 2020 to 2025). "Studies have highlighted that bacterial infections cause a significant induction of Reg3γ, suggesting that Reg3γ has a protective role against infection." (PMID 37524871, 2023). "We used qRT-PCR to quantify the expression of inflammatory genes commonly elevated in bacterial infections including the chemokine Cxcl1, cytokines (Il22, Il17a, and Il6), and the bactericidal antimicrobial peptide Reg3g." (PMID 41502946, 2025). "The reduction of microbiota encroachment by β-glucan was accompanied by restoration of the expression of antimicrobial peptide Reg3γ, indicating β-glucan increases the ability for the mucosa to protect against bacterial infection." (PMID 33008466, 2020). "Furthermore, we observed that antimicrobial peptide Reg3γ mRNA expression was significantly increased in the colon tissue, suggesting MACs may increase the ability for the mucosa to protect against bacterial infection." (PMID 32127019, 2020).
inflammation (2 papers, 2020 to 2021). Aberrant reaction of the microcirculation characterized by movement of fluid and leukocytes from the blood into extravascular tissues. "Additionally, since Irgm1-/- mice were not deficient in key host defense cytokines (IL-22, Reg3γ and Reg3β), the results further suggest that C. rodentium outgrowth and mortality of Irgm1-/- mice cannot be explained by “general susceptibility” to intestinal inflammation." (PMID 32453761, 2020).
metabolic disease (2 papers, 2020 to 2023). A congenital disorder (due to inherited enzyme abnormality) or acquired (due to failure of a metabolically important organ) disorder resulting from an abnormal metabolic process. "Our data showed that rhubarb supplementation is sufficient to protect against metabolic disorders induced by a diet rich in lipid and carbohydrates in association with a reciprocal interaction between Akkermansia muciniphila and Reg3γ." (PMID 32987923, 2020). "Herein, we discuss the current knowledge regarding the biology of Reg3γ, its role in various metabolic functions, and new opportunities for therapeutic strategies to treat metabolic disorders." (PMID 37524871, 2023). "Questions remain regarding the role of Reg3γ in metabolic disorders." (PMID 37524871, 2023). "While further understanding of these pathways is needed, stimulation of endogenous Reg3γ in the gut may be a critical component for the treatment of metabolic diseases." (PMID 37524871, 2023).
gastrointestinal disease (1 paper, 2024). A disease that occurs in the gastrointestinal system, excluding the hepatobiliary system. "Accumulating evidence have uncovered the potential role of the REG3g in the development of inflammation-associated gastrointestinal diseases." (PMID 38322259, 2024).
REG3G also shares sentences with these, for which no sentence is quoted: alcohol use disorder (2 papers); viral infection (2); bacterial vaginosis (1); brain tumors (1); Chronic colitis (1); Cirrhosis (1); colorectal cancer (1); Dent disease (1); diabetes (1); enterocolitis (1); gastric cancer (1); Hyperglycemia (1); Hypertension (1); Insulin resistance (1); insulinoma (1); irritable bowel syndrome (1); liver steatosis (1); polycystic kidney disease (1); psoriasis (1); respiratory diseases (1); Sepsis (1); urinary tract infection (1); uveitis (1).